LINC02577 (long independently transcribed non-coding RNA 2577)
Synonyms: AC002384.1; SLINKY; CLAN
Gene: Long non-coding RNA gene on chromosome 7 (106,774,905 to 106,838,480, forward strand). Ensembl gene ENSG00000228742.
Diseases named in the same sentence as LINC02577 in open-access papers:
LINC02577 is named in the same sentence as 11 diseases in open-access papers, as found by Europe PMC text mining. Sharing a sentence is not in itself a finding about the gene and the disease. The quoted sentences say what the papers report.
cancer (3 papers, 2017 to 2021). A tumor composed of atypical neoplastic, often pleomorphic cells that invade other tissues. "Of note, LINC02577 and LINC02609 have not yet been reported in human cancers." (PMID 33869028, 2021).
tumor (2 papers, 2017 to 2023). "At same time, It was found that the expression of LINC02577 and LINC01133 increased in the blood extracellular vesicle of tumor patients, and LINC02577 was statistically significant." (PMID 37173624, 2023).
LINC02577 also shares sentences with these, for which no sentence is quoted: pancreatic adenocarcinoma (2 papers); head and neck squamous cell carcinoma (1); kidney cancer (1); lung adenocarcinoma (1); lung squamous cell carcinoma (1); papillary renal cell carcinoma (1); squamous cell carcinoma (1); squamous cell carcinoma of the cervix (1); stomach adenocarcinoma (1).